ASCL1 (achaete-scute family bHLH transcription factor 1)
Diseases named in the same sentence as ASCL1 in open-access papers (continued):
Sharing a sentence is not in itself a finding about the gene and the disease.
adenocarcinoma (19 papers, 2010 to 2026). A common cancer characterized by the presence of malignant glandular cells. "Furthermore, the activation of the PI3K/AKT1 and ASCL1 signal transduction pathways was shown to be associated with the transformation of adenocarcinoma to SCLC." (PMID 35806042, 2022). "MYCL expression strongly correlates with the neuroendocrine lineage regulators ASCL1 and INSM1 and inversely with adenocarcinoma-associated genes." (PMID 42001796, 2026). "Ascl1 loss in established NEPC causes transient regression followed by recurrence, but its deletion before transplantation abrogates lineage plasticity, resulting in castration-sensitive adenocarcinomas." (PMID 39394434, 2024). "Interestingly, some of the Hmmr-positive adenocarcinoma cells were also positive for Ascl1 and Insm1 suggesting that this subpopulation of adenocarcinoma cells may have overlapping features or may be in the process of transitioning toward the NEPC phenotype." (PMID 37546702, 2023). "In addition, the SCLC component may derive from the adenocarcinoma component through the activation of achaete-scute family bHLH transcription factor 1 (ASCL1) and PI3K/AKT1 signal transduction pathways." (PMID 35806042, 2022). "Ascl1 is not expressed in the luminal adenocarcinoma lineage but is essential for commitment to a neuroendocrine (NE) fate." (PMID 41509338, 2025). "Further examination revealed that ENZ treatment induced the expression of NR1D1/REV-ERBα and LP drivers, such as BRN2, ASCL1, FOXA2, and ONECUT2, in a dose and time-dependent manner in adenocarcinoma cells, with REV-ERBα being the fastest and strongest induced among them." (PMID 41231955, 2025). "Moreover, some NSCLC adenocarcinomas (ADC) exhibit high ASCL1 expression while maintaining a non-NE phenotype, as observed in both the Rousseaux cohort and TCGA datasets." (PMID 40586102, 2025). "ASCL1 has been found to be associated with lack of EGFR mutations, PD-L1 negative expression, and a poor immune cell infiltration in adenocarcinomas with neuroendocrine differentiation, but not to characterize subsets of SCLC with a distinctive clinical outcome." (PMID 35608806, 2022). "In addition, epithelial cells of patient #6 consisted of a group of NE cells (cluster 4, expressing ASCL1, CHGA, and CHGB), a group of basal cells (cluster 8, expressing KRT5, KRT14, and KRT15) as well as the remaining ARhigh luminal cells, presenting mixed features of both adenocarcinoma and NEPC." (PMID 33328604, 2020). "Establishing whether persistent hASH1 nuclear localisation in previously AD cells, or androgen-insensitive cells, is accompanied by an active and sustained global program of ASCL1-mediated, pro-neural gene transcription in apparent dedifferentiated adenocarcinoma cells, is also key." (PMID 31836808, 2019).
infection (17 papers, 2011 to 2025). The state of being infected such as from the introduction of a foreign agent such as serum, vaccine, antigenic substance or organism. "As expected, infection with Pou5f1-mCherry vector induced both Pou5f1 and Ascl1 expression in Notch1/2-deficient Müller glia." (PMID 40388211, 2025). "Eight days after infection, we performed IF and scRNA-seq to evaluate the ability of ASCL1 to reprogram fetal-derived MG." (PMID 38039971, 2023). "At 12 days post infection (dpi), Ascl1 and Neurog2 shared a similar neuronal induction efficiency, about 50% of GFP+ cells (data not shown)." (PMID 35832093, 2022). "A time-course morphological analysis showed that forced expression of ASCL1 induced U251 cells to change morphology as early as five days post infection (dpi)." (PMID 31212628, 2019). "Dox was added 2–4 days post-infection to allow for degradation of Dnmt3a mRNA and protein before inducing Ascl1 expression for direct conversion of MEFs to neurons." (PMID 30644360, 2019). "Lentiviral gene transfer of the proneural factor Ascl1 partially reprogrammed P11/12 Müller glial cells in vitro into retinal progenitors 3 weeks after infection, a process facilitated by microRNA miR-124-9-9*." (PMID 30483060, 2018). "However, ASCL1 expression was markedly reduced in Pen-2 cKO OPCs following infection with either Ascl1-shRNA1-GFP or Ascl1-shRNA2-GFP, confirming efficient knockdown." (PMID 40882640, 2025). "The results of ASCL1 infection in MG were further analyzed using snRNA-seq." (PMID 38039971, 2023). "After 7 days post-infection (dpi), left and right motor cortices were independently microdissected and analyzed for the expression of kinases that might phosphorylate Ascl1." (PMID 36061596, 2022). "As reflected by dual luciferase reporter assay and RT-qPCR results, H. pylori WT infection augmented the luciferase activity and mRNA level of AQP5 promoter, whereas ASCL1 knockdown abrogated this trend." (PMID 35538066, 2022). "In the presence of Ascl1, the combination of these four chemical enhancers further increased the efficiency of generating induced neurons (iNs) (>10-fold enhancement than Ascl1 infection alone without compounds." (PMID 26861316, 2016). "Additionally, ASCL1 mRNA level increased in the gastric mucosa of H. pylori WT-infected mice and peaked at the 9th week of infection, but ΔcagA infection did not alter AQP5 expression in mouse gastric mucosa, which was validated in primary mouse GECs." (PMID 35538066, 2022). "The mRNA levels of PPAR target genes associated with adipocyte differentiation, including ADRP, FABP4, CD36, APOE, APOC1, ASCL1, were strongly induced in THP-1 cells at 6 or/and 48 h after infection by M. leprae but not stimulation by dead M. leprae, as showed by real-time PCR." (PMID 33075048, 2020).
neurodegenerative disease (2 papers, 2017 to 2022). A disorder of the central nervous system characterized by gradual and progressive loss of neural tissue and neurologic function. "In neurodegenerative diseases, late-onset neurodegenerative diseases appear to be less associated with bHLH mutations, and only the Ascl1 gene is associated with neurodegenerative diseases." (PMID 36430421, 2022). "Ascl1 regulates astrocytes and oligodendrocytes by density and distribution in neurodegenerative diseases." (PMID 28719625, 2017).
psychiatric diseases (2 papers, 2021 to 2023). "Second, ASCL1 is involved in neuronal signature formation, the disruption of which is part of the pathogenesis of psychiatric diseases." (PMID 37958729, 2023).
neurodevelopmental disorder (1 paper, 2023). A behavioral and cognitive disorder with onset during the developmental period that involves impaired or aberrant development of intellectual, motor, or social functions. "We found that functional knockout of ASCL1 in the model cell line SH-SY5Y leads to the deregulation of genes associated with SZ and other neurodevelopmental disorders." (PMID 37958729, 2023).
ASCL1 also shares sentences with these, for which no sentence is quoted: hepatocellular carcinoma (3 papers); large cell neuroendocrine carcinoma (3); medulloblastoma (3); neurological diseases (3); squamous cell carcinoma (3); Alzheimer disease (1); aneurysm (1); Angelman syndrome (1); astrocytic tumor (1); bacterial infections (1); bone tumor (1); brain cancer (1); breast tumours (1); Cardiovascular Diseases (1); cervical intraepithelial neoplasia (1); chronic lymphocytic leukemia (1); COVID-19 (1); diabetic neuropathy (1); Dystonia (1); ependymal tumor (1); ependymoma (1); epilepsy (1); gastric tumor (1); Hepatic steatosis (1); language disorder (1); large cell carcinoma (1); lung squamous cell carcinoma (1); microlissencephalies (1); Mowat-Wilson syndrome (1); neural tube defect (1).
A further 13 diseases each share a sentence with ASCL1 in 1 paper.